PMAIP1 (phorbol-12-myristate-13-acetate-induced protein 1)
Diseases named in the same sentence as PMAIP1 in open-access papers (continued):
Sharing a sentence is not in itself a finding about the gene and the disease.
tumor (124 papers, 2010 to 2026). "Our analysis revealed that PMAIP1 expression is associated with tumor inflammation, angiogenesis, and EMT." (PMID 41323776, 2025). "The down-regulation of Gadd45a and Pmaip1 indicated that in addition to affecting the cell cycle, conotoxin may also cause DNA damage and induce tumor cell formation, leading to cell canceration." (PMID 37828502, 2023). "To assess the impact of PMAIP1 knockdown on tumor proliferation and metastasis, we utilized the proliferation marker Ki67 and the metastasis markers MMP2 and MMP9 for further analysis." (PMID 39944827, 2025). "PMAIP1 exerts a tumor suppressor effect by regulating apoptosis, DNA damage, and mitochondrial dysfunction, providing potential target support for the treatment of TNBC." (PMID 41476687, 2025). "We found that knockdown of PMAIP1 significantly inhibited the sphere-forming ability of the tumor cells." (PMID 41323776, 2025). "In this study, we conducted a comprehensive analysis utilizing the databases, supplemented by validation with clinical tumor samples and cell lines, and identified elevated expression levels of PMAIP1 in FTC." (PMID 39944827, 2025). "The expression of PMAIP1 (NOXA) was significantly higher in the tumor tissues compared to normal tissues, as demonstrated by TCGA analysis." (PMID 40523886, 2025). "By inhibiting tumor cell viability and disrupting cellular homeostasis through multiple mechanisms, PMAIP1 underscores its potential as a therapeutic target." (PMID 41476687, 2025). "Among the other highly modulated genes were the Phorbol-12-Myristate-13-Acetate-Induced Protein 1 (PMAIP1), a tumour suppressor gene frequently downregulated in PDAC, which was robustly modulated (FC: +2.28)." (PMID 36359879, 2022). "Of interest, our analysis highlighted that, independently of the nature of malignant B cells, the pro-apoptotic BH3-only BCL2L11 and PMAIP1 are deeply repressed in tumor niches, suggesting a central role of the microenvironment in their regulation." (PMID 30666297, 2018). "Of interest, our analysis highlighted that, independently of the nature of malignant B cells, the pro-apoptotic BH3-only BCL2L11 and PMAIP1 genes were deeply repressed in tumor niches." (PMID 30666297, 2018). "This indicates that targeting PMAIP1 may achieve the treatment of FTC by altering the tumor immune microenvironment." (PMID 40476267, 2025). "The findings indicated that PMAIP1 knockdown significantly reduced tumor weight and tumor volume." (PMID 39944827, 2025). "Furthermore, multi-omics analysis indicates that PMAIP1 influences the tumor immune microenvironment by regulating glucose metabolism." (PMID 41415282, 2025). "In addition, changes in the expression level of PMAIP1 will affect the quantity and proportion of various immune cells in the patient’s tumor tissue." (PMID 40476267, 2025). "Thus, high PMAIP1 expression should be regarded more as a marker of tumor aggressiveness than a straightforward tumor suppressor." (PMID 41476687, 2025). "We also note the proapoptotic protein PMAIP1 (NOXA) that was downregulated in the drug-adapted tumors, and transcription factors NFIX, EGR1, and HES2 implicated in tumor promotion or suppression, which were differentially affected by LT everolimus and the drug combination." (PMID 39541354, 2024).
tumor (continued). "Although SLC25A5, ACSF2, MFF, and PMAIP1 have not been previously linked to PE, they are known to significantly influence mitochondrial function and tumor cell death." (PMID 39916955, 2024). "Among these significant genes of IL-4 signaling are CFLAR, ALOX5, PMAIP1, EGR1, NCF2, SLC39A8, and PEG10 which have been reported to be associated with tumor progression or chemotherapy-drug resistance through effecting proliferation and apoptosis in previous studies." (PMID 33506057, 2021). "We propose that GADD45B and PMAIP1 be considered putative tumor suppressive factors in NSCLC that might be useful as prognostic markers during NSCLC therapy." (PMID 31296259, 2019). "It has been reported that GADD45B and PMAIP1 have significant roles in anti-proliferation and apoptosis, suggesting that they may function as tumor suppressors." (PMID 31296259, 2019). "This study indicates that GADD45B and PMAIP1 could be promising tumor suppressors for NSCLC and might be useful as prognostic markers for use in NSCLC therapy." (PMID 31296259, 2019). "In this context, our findings support a model in which PMAIP1 can promote mitochondrial apoptosis via the Bax/Bcl‐2 axis and ROS‐mediated dysfunction in vitro, but its clinical link to poor outcomes reflects context‐dependent regulation within the tumor microenvironment." (PMID 41476687, 2025). "The findings demonstrated that PMAIP1 knockdown significantly suppressed the growth of FTC tumors in vivo, as evidenced by reductions in both tumor weight and volume." (PMID 39944827, 2025). "This study examined the expression level of PMAIP1 in FTC through comprehensive analysis of databases, tumor tissues, and cell lines." (PMID 39944827, 2025). "PMAIP1, a member of the pro-apoptotic BCL-2 family (specifically the BH3 subfamily), regulates apoptosis and proliferation in various tumor cells." (PMID 39916955, 2024). "The remaining four PCRGs (ASPDH1, PPP1R13L, PMAIP1, and KLHL35) showed higher expression levels in tumor tissues than in pericardial tissues." (PMID 37190215, 2023). "Transcripts of well-established tumor suppressor genes (Klf6, CD82) and positive regulators of apoptosis (Pmaip1) were found to be suppressed in Eμ-TCL1;CXCR4C1013G." (PMID 34363012, 2021). "Taken together, the results suggest that GADD45B and PMAIP1, when negatively regulated by TFAP2C, can act as tumor suppressive factors inhibiting NSCLC tumorigenesis." (PMID 31296259, 2019). "Based on these exploratory findings, best subset selection identified a two-gene transcriptomic candidate signature comprising PMAIP1 and GADD45A, which showed promising discriminative performance in internal cross-validation and an external tumor-versus-adjacent validation cohort." (PMID 42278359, 2026). "These phenomena strongly suggest that PMAIP1 is a key regulator of apoptosis in TNBC, and its dysregulation may contribute to tumor progression." (PMID 41476687, 2025). "PMAIP1, belongs to pro-apoptotic subfamily within the BCL-2 protein family, referred to as the BCL-2 homology domain 3 (BH3)-only subfamily, which regulates apoptosis and proliferation of various tumor cells." (PMID 38372699, 2024).
tumor (continued). "This may include the upregulation of a proapoptotic protein, phorbol-12-myristate-13-acetate-induced protein 1 (NOXA), which may in turn interact with the anti-apoptotic proteins of the Bcl-2 subfamily, Bcl-XL and Bcl-2, resulting in the apoptotic death of the tumour cells." (PMID 36302993, 2023). "However, active effectors (BAX and BAK) or initiator (PMAIP1, BIK and BID) cannot lead to apoptosis in tumours, and these pro‐apoptotic proteins may be sequestered by guardians (BCL2 and BCL2L1) that have more potent enhancer activity to propel the anti‐apoptotic mechanisms." (PMID 32419250, 2020). "Subsequently, FTC133 and FTC238 cells, with stable PMAIP1 knockdown and negative control, were subcutaneously injected into the left forelimb armpit of NTG mice, and tumor tissues were dissected post-experiment for further analysis." (PMID 39944827, 2025).
infection (17 papers, 2009 to 2023). The state of being infected such as from the introduction of a foreign agent such as serum, vaccine, antigenic substance or organism. "Among the infection-specific ISGs upregulated during ΔHA-Cre infection are genes associated with apoptosis (Ripk2, Casp1, Ifi27, Pmaip1) and E3 ubiquitin ligases and proteasome genes, some of which are known to be involved in MHC-I antigen processing (Neurl3, Rnf19b, Psmb9)." (PMID 32790753, 2020). "At this point in time MAH infection caused a balanced expression of PMAIP1 in donor 1 compared to the non-infected control, while the other two donors showed even down-regulation of PMAIP1 upon MAH infection." (PMID 21629653, 2011). "Last, we also observed upregulation of NOXA (PMAIP1) during MVA infection of THP-1s17,72." (PMID 38065956, 2023). "In addition, one gene encoding another BH3-only protein, PMAIP1 (phorbol-12-myristate-13-acetate-induced protein 1; also known as NOXA; logFC = 3.89), also showed an increased expression in chronic stage of infection." (PMID 28487699, 2017). "Four of these genes also showed >1.5 fold up-regulation in H5N1- compared with H1N1-infected cells at 3 h post-infection: TNF, IFN-induced protein with tetratricopeptide repeats 2 (IFIT2), macrophage inflammatory protein 1-β (CCL4L1), and phorbol-12-myristate-13-acetate-induced protein 1 (PMAIP1)." (PMID 20011590, 2009).
PMAIP1 also shares sentences with these, for which no sentence is quoted: mantle cell lymphoma (14 papers); prostate carcinoma (10); colon cancer (9); liver cancer (5); hepatocellular carcinoma (4); chronic lymphocytic leukemia (3); diffuse large B-cell lymphoma (3); glioblastoma (3); hematologic cancers (3); mesothelioma (3); B cell lymphoma (2); choroidal melanoma (2); colorectal adenocarcinoma (2); colorectal tumors (2); embryonal carcinoma (2); esophageal squamous cell carcinoma (2); hematologic malignancies (2); lung adenocarcinoma (2); medulloblastoma (2); rhabdomyosarcoma (2); sarcoma (2); squamous cell carcinoma (2); T-cell acute lymphoblastic leukemia (2); adenomyosis (1); amyloid (1); anemia (1); asthma (1); autoimmune disease (1); B-cell acute lymphoblastic leukemia (1); bladder tumors (1).
A further 35 diseases each share a sentence with PMAIP1 in 1 paper.